GADD45G (growth arrest and DNA damage inducible gamma)
Diseases named in the same sentence as GADD45G in open-access papers (continued):
Sharing a sentence is not in itself a finding about the gene and the disease.
cancer (31 papers, 2008 to 2025). A tumor composed of atypical neoplastic, often pleomorphic cells that invade other tissues. "We found that GADD45G was associated with various cancer-related pathways including cell cycle, carbon metabolism, and peroxisome, which was consistent with previous studies." (PMID 37833694, 2023). "In addition, inhibition of GADD45A and GADD45G expression is critical to the survival of cancer cells the mutation frequency and specific functions of GADD45 family members in different types of cancer remain to be determined." (PMID 38070141, 2023). "Interestingly, low expression of Gadd45g has been associated with various cancers, indicating that it normally suppresses cellular growth and proliferation." (PMID 34884738, 2021). "Notably, SAP-induced genes such as Gadd45g are associated with cancer." (PMID 27239478, 2016). "Only 6 CDGs appeared under cell cycle and those were ANAPC13, ANAPC5, MAD2L2, GADD45G, CCND2, and surprisingly MYC — a gene often implicated as a cancer driver." (PMID 39774001, 2025). "The induction and activation of mda-7/IL-24 by NSAIDs result in the upregulation of GADD45A and GADD45G, which are crucial for the execution of cancer cell death through JNK activation." (PMID 41018072, 2025). "We analyzed the expression of GADD45G across various tumors and corresponding normal tissues using pan-cancer datasets from TCGA, TARGET, and GTEx." (PMID 41018072, 2025). "In order to identify and develop small molecule drugs capable of inducing GADD45G expression in cancer cells, we examined the correlation between GADD45G expression and various cancer-related drugs using the CTD database." (PMID 41018072, 2025). "An inverse relationship was observed between GADD45G and NF-κB for the control of cancer cell death; when GADD45G was activated, the other NF-κB-mediated signal was suppressed." (PMID 36135176, 2022). "Next, we evaluated Gadd45g and Tsc1 expression in human PSCs and cancer cell lines (PANC-1, PACA2, and ASPC1)." (PMID 35211358, 2022). "Due to high homology of GADD45 genes, GADD45A and GADD45G exert similar effects on the development of cancers." (PMID 34601500, 2021). "Our research not only demonstrated Gadd45g as a pivotal differentiation inducer of ESCs, but also will help people explore more drugs to better control cell differentiation and cancer treatment." (PMID 34601500, 2021). "Moreover, we explored the correlation between GADD45G and various cancer drugs through the CTD database." (PMID 41018072, 2025). "The forest map generated through merging GADD45G expression data in HCC and non-cancer liver samples from RNA-seq dataset and microarray datasets also confirmed the significant low expression of GADD45G mRNA in HCC (SMD, − 0.78; 95% CI, − 1.03 to − 0.54; p = 0.000)." (PMID 37833694, 2023). "Numerous reports have shown that ATF3 and GADD45G play critical roles in cancer." (PMID 35684411, 2022). "Indeed, genistein treatment of NCCIT cells led to the induction of GADD45A and GADD45G expression with other cancer types." (PMID 18847459, 2008). "In conclusion, GADD45G may serve as a promising biomarker for cancer diagnosis and therapy." (PMID 41018072, 2025). "In addition, GADD45g plays a role in regulating proliferation in different cancers." (PMID 35928721, 2022). "The growth arrest and DNA damage-inducible gene gamma (GADD45G), an important member of GADD45 family, has been connected to the development of certain human cancers." (PMID 37833694, 2023). "To validate the binding of the genes with these four antibodies, we examined 8 candidate genes that are involved in cancer progression, including Esr1, Bcas3, and Bard1, as well as Crebbp, Myc, Rel, Gadd45g, and Shcbp1 (not shown)." (PMID 40157910, 2025). "GADD45G promotes cell differentiation through negative regulation of the phosphoinositide 3-kinase/AKT/mTOR (PI3K/AKT/mTOR) pathway, and, consequently, its downregulation leads to activation of this pathway to drive cancer." (PMID 40188944, 2025).
cancer (continued). "Interestingly, following activity onset (CT38), pathways established to be involved in cancer-induced muscle wasting, including JAK-STAT, tumor necrosis factor (TNF), and FoxO signaling pathways, were enriched from genes increased in KPC mice (e.g., Jak3, Osmr, Nfkbia, Bcl3, Gadd45g, and Cebpb)." (PMID 40349340, 2025).
infection (6 papers, 2011 to 2023). The state of being infected such as from the introduction of a foreign agent such as serum, vaccine, antigenic substance or organism. "Within the liver parenchyma close to the lesion and peri-parasitic infiltrate, Gadd45γ expression was observed at day90 and markedly increased at days 180, 270 and 360 post-infection, with staining intensities from “moderate” to “strong”." (PMID 22253905, 2012). "In addition, our genetic analysis suggested that GADD45G from rs10114707 locus that reached genome-wide significance could be a potential core gene that regulates a cytokine network upon Candida infection." (PMID 34512620, 2021). "Among them, eight DEGs (RF00100, NXPH2, SEC61G, GADD45G, TUBAL3, LIPE, CSRNP1, and FAM20A) were shared across different comparison groups after FX0910 infection." (PMID 37982609, 2023). "Before day60, Gadd45γ mRNA expression was unchanged; it then increased from day60 (∼3.23-fold) to 360 (∼3.47-fold) and peaked at day180 (∼7.86-fold) post-infection; it was significantly different between E. multilocularis-infected and non-infected mice at days 180 and 360 post-infection (P < 0.05)." (PMID 22253905, 2012).
Neurological Disease (2 papers, 2016 to 2024). "Currently, there is a paucity of research investigating the underlying mechanisms of GADD45 family, particularly focusing on GADD45α and GADD45γ, in relation to neurological disorders." (PMID 38332860, 2024). "Despite reports on the expression patterns and mechanisms of GADD45β in neurological disorders, a comprehensive synthesis and analysis of the entire GADD45 family, particularly GADD45α and GADD45γ, across diverse diseases is still lacking." (PMID 38332860, 2024).
cardiovascular disease (1 paper, 2022). "By searching for the potential targets of miR-877-3p, we found that among the potential targets regulated by miR-877-3p, GADD45g, NSUN2, YTHDF2 and MTUS1 have regulatory roles in the involvement of cardiovascular disease 30-32." (PMID 35928721, 2022).
hematologic malignancies (1 paper, 2015). "Although several studies have focused on the relationship between GADD45γ gene expression and methylation in hematologic malignancies and solid tumors, there are limited data in the literature about the involvement of GADD45γ methylation and protein expression in DLBCL development." (PMID 25912017, 2015).
renal diseases (1 paper, 2024). "We expect that more studies will follow our study to see the implications of the urinary GADD45G protein in renal diseases." (PMID 39767752, 2024).
GADD45G also shares sentences with these, for which no sentence is quoted: epilepsy (3 papers); lymphoma (3); pituitary adenomas (3); Insulin resistance (2); Obesity (2); acute lymphoblastic leukemia (1); allergic asthma (1); autoimmune disease (1); central nervous system disorder (1); Cirrhosis (1); Cryptosporidium infection (1); disc degeneration (1); hyperplasia (1); infectious keratitis (1); influenza (1); intervertebral disc degeneration (1); ischemia (1); liver steatosis (1); male infertility (1); multiple myeloma (1); myeloproliferative neoplasm (1); myocardial hypertrophy (1); Nasu-Hakola disease (1); nephritis (1); non-small cell lung carcinoma (1); prion disease (1); renal fibrosis (1); sarcopenia (1); schizophrenia (1); scrapie (1).
A further 2 diseases each share a sentence with GADD45G in 1 paper.